DNAJC22 (DnaJ heat shock protein family (Hsp40) member C22)
Description:
May function as a co-chaperone.
Synonyms: wus; FLJ13236
Tractability: Antibody: UniProt predicts a signal peptide or a membrane-spanning region. PROTAC: ubiquitination databases record sites on it.
Gene: Protein-coding gene on chromosome 12 (49,345,607 to 49,357,546, forward strand). Ensembl gene ENSG00000178401.
Subcellular location: Membrane
Subcellular location (Human Protein Atlas): Vesicles
Gene Ontology:
Molecular function: protein binding
Cellular component: membrane
Genetic constraint (gnomAD): Loss-of-function variants: 26 observed, 26.26 expected, observed/expected ratio (o/e) 0.99, 90% interval 0.73 to 1.37. The upper end of that interval is the gene's LOEUF score, 1.37, which puts it in group 5 of 6, group 1 being the genes least tolerant of losing a copy. Missense variants: 434 observed, 439.03 expected, observed/expected ratio (o/e) 0.99, 90% interval 0.91 to 1.07. Synonymous variants: 160 observed, 173.56 expected, observed/expected ratio (o/e) 0.92, 90% interval 0.81 to 1.05.
Homologues: Orthologues: chimpanzee DNAJC22 (99% identical), macaque DNAJC22 (96% identical), dog DNAJC22 (87% identical), pig DNAJC22 (86% identical), mouse Dnajc22 (82% identical), rat Dnajc22 (82% identical), tropical clawed frog dnajc22 (59% identical), zebrafish dnajc22 (50% identical), Drosophila melanogaster wus (27% identical).
Diseases named in the same sentence as DNAJC22 in open-access papers:
DNAJC22 is named in the same sentence as 5 diseases in open-access papers, as found by Europe PMC text mining. Sharing a sentence is not in itself a finding about the gene and the disease.
DNAJC22 shares sentences with these, for which no sentence is quoted: colorectal cancer (1 paper); hepatocellular carcinoma (1); infection (1); insulinoma (1); tumor (1).